CD1B (CD1b molecule)
Diseases named in the same sentence as CD1B in open-access papers (continued):
Sharing a sentence is not in itself a finding about the gene and the disease.
CD1B also shares sentences with these, for which no sentence is quoted: dyslipidemia (2 papers); lung carcinoma (2); lupus (2); adenocarcinoma (1); adrenoleukodystrophy (1); asthma (1); Fabry disease (1); Gaucher disease (1); hematological neoplasms (1); hyperlipidemia (1); idiopathic pulmonary fibrosis (1); mycobacterial infection (1); periodontitis (1); stomach cancers (1); thymoma (1); tuberculoid leprosy (1); vitiligo (1); X-linked adrenoleukodystrophy (1).